INS (insulin)
Diseases named in the same sentence as INS in open-access papers (continued):
Sharing a sentence is not in itself a finding about the gene and the disease.
Obesity (continued). "Here we characterized the glucose-insulin axis in the first trimester of human pregnancy and assessed the effect of maternal obesity and fat mass." (PMID 33154737, 2020). "Here the authors report that obesity increases the levels of miR-802, which impairs insulin transcription and secretion by targeting NeuroD1 and Fzd5." (PMID 32286278, 2020). "Systemic inflammation damages the pancreatic beta cells, disrupts insulin action and mediates glucose intolerance in obese individuals, and LPS-derived chronic low-grade inflammation is one of the hallmarks of obesity." (PMID 32013093, 2020). "Obesity stimulates various inflammatory pathways in adipose tissue, disturbs insulin levels, and creates oxidative stress, which all play an essential role in the development of NAFLD." (PMID 32823604, 2020). "Our cohort of children with obesity showed hyperinsulinaemia, but this excess of insulin secretion was able to maintain normal glucose levels." (PMID 32128247, 2020). "Adiponectin, encoded by the ADIPOQ gene, is of particular interest in metabolic syndrome because of its inverse relation with insulin sensitivity and obesity." (PMID 33232281, 2020). "Our results show that obese SM/J mice undergo restoration of functional β‐cell mass, providing an opportunity to explore how compensatory insulin production can be achieved in the context of obesity." (PMID 33113267, 2020). "Protein kinase B (AKT) activation through mTORC2 activation by Sestrins leads to improved insulin sensitivity in obesity and diabetes." (PMID 33425907, 2020). "In our study, we examined how mirtazapine affects metabolic parameters, insulin profiles, glucose metabolism, and obesity changes in high-fat diet-fed C57BL6/J mice." (PMID 32824002, 2020). "In one study, JNK1 was knocked down in skeletal muscles using the Cre-lox system and the authors found that muscle-specific JNK1-null mice were protected from obesity-induced skeletal muscle insulin resistance." (PMID 32183037, 2020). "Intriguingly, activation of these pathways is regulated by leptin, the proinflammatory mediator released mainly by adipocytes that link the immune system with obesity-related insulin and leptin resistance." (PMID 32824322, 2020). "In this context, chlodronate liposome macrophage depletion rescues glucose-induced insulin secretion in models of genetic obesity and in palmitate-infused mice." (PMID 32140136, 2020). "It was shown that lifestyle modification inducing weight loss, including increased physical activity and low-fat diet, increased brain insulin sensitivity in people with obesity as assessed by intranasal insulin spray." (PMID 32849302, 2020). "The genetically modified Bacillus subtilis SCK6 strain BsS-RS06550 showed beneficial effects toward obesity, fasting blood glucose, insulin resistance, hepatic steatosis and fat accumulation." (PMID 32334588, 2020). "Contrary to leptin, circulating adiponectin levels are decreased in obesity and are inversely correlated with the body mass index (BMI), glycaemia, and circulating insulin levels, as well as with the risk of developing T2DM, obesity, and CVDs." (PMID 33081064, 2020). "A similar insulin-resistant phenotype has also been reported in leptin-deficient ob/ob mice fed the GAN diet (GAN ob/ob-NASH mice), an obesity-prone accelerated model of NASH, which lends further support to the translatability of GAN diet-based mouse models." (PMID 32631250, 2020). "Previous studies have reported an increase in PPARγ expression by obesity in adipose tissue in an animal model and in humans, perhaps reflecting an attempt of the increasing adiposity to maintain insulin sensitivity." (PMID 32731460, 2020). "In either case, there remains limited data in humans with obesity or T2D confirming the effects of exercise on brain insulin sensitivity in relation to glucose metabolism." (PMID 32849302, 2020).
Obesity (continued). "Cancer‐induced skeletal muscle wasting and obesity present common skeletal muscle pathological mechanisms, such as insulin resistance, inflammatory state, and oxidative stress." (PMID 33053604, 2020). "Major hormones that shift in concentration in obesity (especially menopause-induced obesity) include insulin, estrogen, and adipokines." (PMID 32742493, 2020). "Under insulin‐stimulated conditions, maternal exercise attenuated the effects of paternal obesity in adult offspring." (PMID 32539156, 2020). "The elevation in methylated INS in youth with obesity is reminiscent of the elevations in methylated INS we reported in youth with new-onset T1D." (PMID 32736653, 2020). "Long-term glucose marker HbA1C had a significant and reliable weight in the metabolic profile, indicating that disturbed glucose and insulin metabolism is another pathway linking obesity to reduced GMV." (PMID 31427957, 2019). "The increase in FFA due to overweight or obesity can trigger IR, which further inhibits insulin signalling and insulin-stimulated glucose uptake in skeletal muscles and increases glucose delivery by the liver." (PMID 31086234, 2019). "Although MOTS‐c showed significant effects on diet‐induced obesity and insulin sensitivity, the precise mechanisms are still being investigated." (PMID 31293078, 2019). "miR-221 is involved in the development of obesity and has been reported to negatively regulate insulin sensitivity." (PMID 31828133, 2019). "Obesity and inflammation affect the insulin transport to the brain and low expression of IR has been reported in patients with T2D." (PMID 31417349, 2019). "With obesity, the adipocyte secretome changes toward greater secretion of pro-inflammatory mediators and reduced production of anti-inflammatory or insulin sensitizing factors." (PMID 31130916, 2019). "We recently found that the ingestion of sucralose before an oral glucose tolerance test (OGTT) increased the plasma insulin response and decreased whole-body insulin sensitivity in people with obesity." (PMID 31877631, 2019). "Obesity elicited a chronic, low-grade systemic inflammatory response that was due to a combination of increased insulin resistance and an increased production of inflammatory mediators by expanding the pool of adipocytes." (PMID 31623319, 2019). "Our observations need further validation using tracing of FFAs and evaluation of their turnover in the face of changing insulin concentrations as well as in children with similar degrees of obesity yet different lipid partitioning patterns." (PMID 30637483, 2019). "Compared with water treatment, sucralose ingestion increased glucose-stimulated insulin responses only in participants with obesity." (PMID 31877631, 2019). "In conclusion, ginsenoside Rb1 exerts significant anti-obesity, anti-hyperglycemic, and anti-diabetic effects by regulating the effects of glycolipid metabolism and improving insulin and leptin sensitivities." (PMID 30823412, 2019). "As the common pathology in obesity and type 2 diabetes, IR is defined as a state in which cells fail to respond to insulin, resulting in the development of hyperglycemia." (PMID 31803062, 2019). "In contrast, adiponectin can improve insulin sensitivity, enhance fatty acid oxidation, and energy expenditure, and its secretion is often decreased in obesity condition." (PMID 30658634, 2019). "A recent systematic review indicated evidence of a link between sleep parameters and obesity, hypertension, and insulin sensitivity, but there were an insufficient number of high-quality studies available for assessing causality." (PMID 30934733, 2019). "This indicates that different exercise prescriptions may provide favorable outcomes to different insulin sensitive tissues, a finding that with time will likely be considered when physical exercise is prescribed to manage metabolic disturbances associated with obesity." (PMID 31105582, 2019).
Obesity (continued). "During Gantulga’s study, they showed that the use of insulin activated Nesfatin-1 neurons and inhibited the feeding process, which decreased the occurrence of obesity." (PMID 31195699, 2019). "In obesity, insulin‐mediated lipolysis in adipocytes is impaired, leading to an increase in NEFA, which interferes with insulin to affect glucose intake." (PMID 30828530, 2019). "Skeletal muscle insulin signaling was the least affected by obesity but was altered by exercising obese dams." (PMID 31466137, 2019). "Both cytokines have been demonstrated to promote glucose tolerance, insulin sensitivity, resistance to diet-induced obesity, and upregulated expression of lipolysis and beta-oxidation genes in white and beige fat." (PMID 31042465, 2019). "Increased circulating concentrations of adiponectin are generally related to beneficial metabolic effects, such as improved insulin sensitivity and decreased levels of obesity and insulin resistance." (PMID 31586115, 2019). "Zn also improves insulin sensitivity in individuals with obesity and there is also evidence of high insulin sensitivity in elite athletes." (PMID 30909645, 2019). "Specifically, it upregulated the expression of Phosphoinositide-3-kinase, a central mediator of the intracellular signal transduction of insulin sensing, whose transcriptional downregulation has been related to obesity induced IR." (PMID 31521172, 2019). "The high capacity of NLE-SCI-57 to stimulate the uptake of glucose in terminal adipocytes, and its low adipogenic capacity (pro-obesity), make it an optimal candidate for replacing native insulin." (PMID 31798448, 2019). "Metabolic parameters in serum samples, including lipidogram, glucose, leptin, ghrelin and insulin and obesity markers (BMI, W/H ratio, HOMA) were assayed and compared with values from 130 healthy female volunteers (controls)." (PMID 30635060, 2019). "Concordantly, the deletion of miR-155 in mice prevented diet-induced obesity, improved insulin sensitivity, and abrogated adipocyte hypertrophy and AT inflammation." (PMID 31627295, 2019). "Plasma insulin and C-peptide mean and peak concentrations, as well as iAUCs, were significantly higher in participants with obesity than in normal-weight participants (all p-values < 0.02)." (PMID 31877631, 2019). "The pathology of obesity is multifold and includes aberrant insulin growth factor/insulin signaling, altered steroid production, and chronic systemic and local inflammation." (PMID 31015794, 2019). "Meanwhile, obesity-induced insulin resistant status with long-term IL-4 overexpression was also established by feeding IL-4-injected mice with HFD (HFD + IL-4 mice)." (PMID 31814802, 2019). "Obesity is associated with insulin resistance, a well-established pre-cursor to T2DM; however, elevated insulin levels also promote the development of certain obesity related cancers such as colorectal, pancreatic, liver and endometrial." (PMID 31018563, 2019). "Three main patterns of multitrait association emerged from this analysis, two of them reflecting defects in insulin secretion and insulin action, respectively, and a third characterized by obesity and dyslipidemia." (PMID 31322649, 2019). "The carbohydrate-insulin model of obesity verifies the logic that the increased ratio of insulin to glucagon concentration after consuming a diet with a high glycemic load directs metabolic fuels from consumption toward storage in adipose tissue." (PMID 31330812, 2019). "High apoA-IV pre-surgical levels are related to improved insulin sensitivity after Roux-en-Y bypass surgery, which is an effective treatment for obesity and obesity-related co-morbidities, such as diabetes." (PMID 30959835, 2019). "Obesity was characterized by increased levels of free T, total and free E2, hsCRP, fasting insulin and glucose, greater WC, WHR and HOMA-IR, and by decreased SHBG and ISI value." (PMID 31652917, 2019).
Obesity (continued). "Disentangling the connection between obesity, the insulin-IGF axis, endogenous hormones, inflammatory markers, and their molecular interaction is vital." (PMID 30931341, 2019). "Prenatal dexamethasone treatment has been shown to enhance the susceptibility of offspring to postnatal HF diet-induced programmed obesity, insulin dysregulation, and hypertension." (PMID 30658634, 2019). "Our results suggest the involvement of lipid metabolism, glucagon and insulin signaling pathways in obesity-driven alterations of adipocyte functions related to carcinogenesis." (PMID 30838002, 2019). "Both male and female sex hormones, as well as sex chromosomes themselves, contribute to the development of obesity and intervene in the control of insulin homeostasis and blood pressure." (PMID 31262349, 2019). "In particular, the relevance of insulin in the regulation of leptin levels and involvement in insulin downstream signaling indicates the key role of leptin in obesity-induced IR, which is under the thorough consideration of scientists." (PMID 31408957, 2019). "These memory-promoting effects of insulin appear to mirror the peripheral metabolic effects of insulin in that HFD consumption and obesity are associated with dysregulated IR signaling pathways." (PMID 31057368, 2019). "This study provides novel evidence for an etiological role of insulin in RCC, as well as confirmatory evidence that obesity and DBP influence RCC risk." (PMID 30605491, 2019). "We conclude that obesity status affects the relationship between protein intake and insulin sensitivity in late pregnancy." (PMID 31514469, 2019). "The implications of this carbohydrate/insulin model for obesity on the development of cancers is yet to be fully elucidated." (PMID 30809194, 2019). "The likelihood of increased triglycerides and decreased HDL cholesterol and decreased insulin sensitivity as a consequence of obesity has been shown in children." (PMID 31293520, 2019). "Insulin/MAPK/mTORC1 signaling in the skeletal muscle was largely unaffected by obesity alone but was influenced more extensively by exercising the obese dams." (PMID 31466137, 2019). "In skeletal muscle and perirenal adipose tissue, cross-fostering highlighted the opposite effect in offspring exposed to maternal obesity during gestation, suggesting insulin sensitivity." (PMID 31300679, 2019). "We also found that SSE reduced the severity of diet-induced obesity, although, as only a moderate effect was observed, it appears that the reduced body weight cannot account for the normalization of insulin sensitivity and hepatic steatosis induced by SSE." (PMID 31847157, 2019). "We and others have suggested that a low degree of liver steatosis is a strong feature of insulin sensitivity in obesity." (PMID 31071971, 2019). "We extensively review the available evidence pertaining to the influence of insulin secretion and sensitivity, obesity, autoimmunity, lifestyle, growth hormone, and sex hormone replacement therapy on the occurrence of DM in these patients." (PMID 30792694, 2019). "Obesity has several effects on renal physiology, including insulin resistance, inflammation, oxidative stress, renin-angiotensin-aldosterone, and hyperlipidemia." (PMID 31498850, 2019). "Whilst caution should be made in extrapolating these findings to humans, understanding the metabolic mechanisms of obesity and insulin resistance offers the potential target for nutritional intervention during breastfeeding." (PMID 31300679, 2019). "During obesity, insulin signaling pathway is deregulated and a state of low grade systemic inflammation is established." (PMID 31244863, 2019). "In the context of obesity, peripheral macrophages also become resistant to insulin exhibiting increased glycolysis, important for the regulation of their M2-like polarization status." (PMID 31244863, 2019).
Obesity (continued). "There have been reports that rodents fed a high-fat diet for 12 months to induce obesity and insulin resistance displayed increased islet size and β-cell volume." (PMID 31372175, 2019). "Recently, several miRNAs have emerged as involved in pathways related to obesity such as adipocyte differentiation, adipokine expression, glucose and lipid metabolism, insulin signalling, oxidative stress, and inflammation." (PMID 31766503, 2019). "A growing body of research has evidenced that dysfunctional adipose tissues, mainly observed during obesity, are characterized by impaired insulin signaling, insulin resistance, adipocyte hypertrophy, and macrophage infiltration." (PMID 31151180, 2019). "KEGG pathway analysis showed that two DEmRNAs, Slc27a1 and Slc2a4, were involved in the insulin resistance signaling pathway, which is closely related to obesity (Yu, Kim & Lee, 2017)." (PMID 30842902, 2019). "Challenging situations, such as obesity-induced infertility, can be reversed by modulating insulin signaling." (PMID 31009498, 2019). "The primary cause of T2D is obesity-driven insulin resistance (IR) in white adipose tissue (WAT), liver, and skeletal muscle, combined with impaired secretion of insulin by pancreatic β-cells to overcome this resistance." (PMID 31085992, 2019). "It is well-established that lipid partitioning, i.e., the pattern of lipid deposition, is a stronger determinant of whole body insulin sensitivity than the degree of obesity per se." (PMID 31474943, 2019). "We identified pathways in cancer, MAPK signaling pathway, focal adhesion as specifically enriched and, most interestingly, other enriched pathways that are highly relevant to the obesity phenotype, such as metabolic pathways and insulin signaling pathway." (PMID 31921306, 2019). "The changes induced by obesity and exercise were tissue‐specific and related to alterations in tissue lipid, protein and glycogen content and plasma insulin, leptin and triglyceride concentrations." (PMID 31466137, 2019). "The ability of short-term depletion of T cells in fat by anti-CD3 to reverse insulin resistance in early-stage obesity emphasizes the key role of adipose T cells in improving glucose tolerance and insulin sensitivity." (PMID 31191541, 2019). "Our focus on endometrial cancer stems from the fact that this tumor is tightly correlated with obesity and, in particular, with the insulin/IGF1 signaling pathways." (PMID 31320996, 2019). "This is primarily because DGAT1 mouse knockout (KO) models are resistant to diet-induced obesity, show decreased levels of tissue triglycerides, and have increased sensitivity to insulin and leptin." (PMID 31345219, 2019). "Using this method, we found that three tumor cell lines associated with obesity (colon cancer [MC38], breast cancer [4T1], and prostate cancer [TRAMP-C3] cells) increase VPDH/VCS in response to physiologic concentrations of insulin." (PMID 31188872, 2019). "It has hypolipidemic, hypoglycemic, insulin-sensitizing, anti-obesity, antioxidant and anti-inflammatory properties in animal models and also in clinical studies, probably due to the activation of AMP-activated protein kinase (AMPK)." (PMID 31658729, 2019). "In conclusion, findings from this study reveal that CT-1 expressed from the scFEM, not the scABD, AT depot was negatively associated with ectopic lipid (visceral adiposity and liver fat) and positively correlated with insulin sensitivity in women with obesity." (PMID 31013924, 2019). "Daily use of the KI composition significantly decreased levels of blood glucose and blood triglycerides, as well as improved the insulin production in islets or reduced development of obesity in STZ-induced diabetic rats or in db/db mice." (PMID 31687407, 2019).